AHR (aryl hydrocarbon receptor)
Diseases named in the same sentence as AHR in open-access papers (continued):
Sharing a sentence is not in itself a finding about the gene and the disease.
vitiligo (continued). "Other studies showed that the expression levels of antioxidant molecules downstream of AhR, such as HO-1, GST, GPx, CAT, and SOD, are also significantly reduced in vitiligo." (PMID 35320978, 2022). "We also found that declined SP1 mRNA level in vitiligo patients and a strongly positive correlation between SP1 and AHR expressions." (PMID 26370050, 2015). "In patients with vitiligo, excessive accumulation of KYNA may induce the expression of CXCL10 in keratinocytes through activation of the AhR pathway, which contributes to the recruitment of CD8 + T cells at the site of lesions." (PMID 40703229, 2025). "In addition, AhR also crosstalks with the JAK-STAT pathway, which is recognized as a key new therapeutic target for vitiligo." (PMID 38361944, 2024). "Indeed, AhR expression was significantly lower in CD4+ T cells and the skin of vitiligo patients than that in healthy controls, and knockdown of AhR increased IL-17A production and decreased IL-22 levels in CD4+ T cells of vitiligo patients." (PMID 35625824, 2022). "Besides, AhR also regulates CD4+ TRM cell differentiation and function, which may conduce to immune protection, and tissue remodeling in vitiligo." (PMID 38361944, 2024). "However, the relationship between AhR-mediated IL-17 expression and vitiligo has not yet been stated." (PMID 33499346, 2021). "Interestingly, most of the therapeutic measures taken to re-pigment vitiligo lesions, i.e., irradiation with narrow-band UVB or photochemotherapy (treatment with 8-methoxypsoralen or khellin and subsequent UVA exposure), have at least the potential to activate AHR signaling." (PMID 31795255, 2019). "We subsequently found reduced peripheral AHR and SP1 transcript expressions in vitiligo and a negative correlation of AHR level with disease duration." (PMID 26370050, 2015).
endometriosis (13 papers, 2005 to 2025). The growth of functional endometrial tissue in anatomic sites outside the uterine body. "The vitamin D receptor (VDR) and aryl hydrocarbon receptor (AHR) are two nuclear receptors which have been associated with endometriosis." (PMID 34155552, 2021). "Various studies on AhR-related gene polymorphisms, as explored by a recent meta-analysis on endometriosis risk in Asian populations, have considered AhR Arg554Lys and AhR nuclear translocator (ARNT) Val189Val as potential candidates." (PMID 27899901, 2016). "DL-PCBs have been the first PCB congeners to be considered in association with endometriosis because, as dioxins, they bind to the aryl hydrocarbon receptor (AhR) and elicit the same spectrum of toxic activities through the same mechanism of action." (PMID 19654915, 2009). "The increase in AHR expression and altered methylation of 14 indicated genes, according to the authors, may be a diagnostic tool to identify a subgroup of women with endometriosis-related infertility." (PMID 35409163, 2022). "Given that VDR and AHR were both previously implicated in endometriosis, in this study we investigated the nuclear and cytoplasmic expression of VDR and AHR in tissues from normal endometrium (in the three physiological phases: proliferative, early, and late secretory) and ovarian endometriosis." (PMID 34155552, 2021). "Specifically, IL-10, an interleukin cytokine produced by Th17 cells, is known to promote the development of ectopic lesions characteristic to endometriosis and is highly secreted when AHR is overexpressed." (PMID 39720712, 2024). "The direct AHR-mediated impact of dioxin on GdA gene transcription and protein secretion suggests a potential connection between TCDD exposure and endometriosis, a known risk factor for preterm birth." (PMID 39720712, 2024). "This study provides a possible starting point for developing more effective drugs specifically targeting VDR- or AHR-expressing cells in the context of endometriosis." (PMID 34155552, 2021). "The comparison of VDR or AHR expression in such tissues is based on the nature of endometriosis, which is defined as “the presence of endometrium-like tissue outside the uterus”." (PMID 34155552, 2021). "In estrogen target tissues such as the endometrium, this mechanism leads to the promotion of cellular proliferation, suggesting a link between AHR activity and endometriosis pathophysiology." (PMID 34155552, 2021). "We demonstrate that in the nuclei of glandular cells in endometriosis, the expression of VDR and AHR is mutually exclusive—when the expression of one receptor is high, the other one is low—suggesting a possible target in the treatment of endometriosis." (PMID 34155552, 2021). "A combined analysis of the possible changes in the relative expression of VDR and AHR is currently missing and could provide more insight into the pathophysiological description of endometriosis." (PMID 34155552, 2021). "By targeting receptors such as PPARs, AhR, and NR4A1, flavonoids demonstrate the capacity to modulate both metabolic and inflammatory pathways, offering a multifaceted approach to managing endometriosis." (PMID 39803270, 2025). "In certain pathological conditions, such as endometriosis, uterine leiomyomas, and presumably PCOS, mRNA expression of transcription factors AHR and ARNT is altered at select target sites." (PMID 38468402, 2024). "For this purpose, an evaluation was performed using tissue from the three normal phases of the endometrium (proliferative, early, and late secretory) and in endometriosis by immunohistochemistry, using anti-VDR and anti-AHR antibodies." (PMID 34155552, 2021). "Additionally, dioxins (through the aryl hydrocarbon receptor) and endocrine disruptors found in diesel exhaust (including through the polycyclic aromatic hyrdrocarbon receptor) may influence the local hormonal milieu surrounding the lesion of endometriosis." (PMID 24225723, 2014).
endometriosis (continued). "The difference in the results of dataset GSE7305 demonstrated that all NRDEGs were statistically significant, and the expression levels of C7, HOOK1, PKP3, AHR, GJB1, and MYO6 in different groups of endometriosis dataset GSE7305 were statistically significant (P < 0.001)." (PMID 37817158, 2023). "Collectively, these findings suggest that interventions targeting the tryptophan–AhR axis—such as probiotics, prebiotics, IDO-1 inhibitors, and AhR modulators—represent a promising, non-hormonal approach to managing endometriosis through microbiome-based immunomodulation." (PMID 40430189, 2025).
medulloblastoma (13 papers, 2014 to 2026). A malignant, invasive embryonal neoplasm arising from the cerebellum. "Previous studies have implicated AHR in cerebellar development and medulloblastoma cell proliferation." (PMID 31924815, 2020). "It should be noted that other genes in the AHR pathway have been implicated in medulloblastoma." (PMID 31924815, 2020). "In cancers of the nervous system, the activity of AhR has been shown to inhibit sonic hedgehog (SHH)-driven medulloblastoma through blocking TGF-β signaling." (PMID 37106727, 2023). "We identified the aryl hydrocarbon receptor (AHR) pathway as a potent tumour suppressor in a SHH medulloblastoma mouse model." (PMID 31924815, 2020). "Examination of the expression of AHR pathway genes in human medulloblastoma cohorts support an important role for the AHR pathway in SHH medulloblastoma biology." (PMID 31924815, 2020). "Observations that impairment of AhR function disturbs the regulation of the cell cycle of cerebellar neuronal precursors suggest that AhR promotes medulloblastoma growth." (PMID 32325928, 2020). "Our analyses of these mice revealed a striking tumour-suppressive role for AHR in mouse SHH medulloblastoma development." (PMID 31924815, 2020). "Together, these findings implicated the TGF-β/SMAD3 pathway in mediating the effect of AHR signalling on proliferation and cell survival of medulloblastoma CPCs." (PMID 31924815, 2020). "Human SHH medulloblastomas with high expression of the AHR repressor (AHRR) exhibited a significantly worse prognosis compared to AHRRlow tumours in two independent patient cohorts." (PMID 31924815, 2020). "That is, AhR promotes the proliferation of medulloblastoma cells and should be regarded as a potential therapeutic target in this disease." (PMID 32325928, 2020). "Together, these findings suggest that reduced AHR pathway activity promotes SHH medulloblastoma progression, consistent with a tumour suppressive role for AHR." (PMID 31924815, 2020). "We propose that TGFβ/SMAD3 inhibition may represent an actionable therapeutic approach for a subset of aggressive SHH medulloblastomas characterised by reduced AHR pathway activity." (PMID 31924815, 2020). "Dever and Opanashuk reported that the AhR was overexpressed in the GNP cells from the developing cerebellum and that abnormal activation/suppression of the AhR led to aberrant regulation of their cell cycle and maturation, suggesting that the AhR stimulates the growth of medulloblastomas." (PMID 29487603, 2018). "Dever and Opanashuk explored the function of the AhR in a medulloblastoma cell line (DAOY)." (PMID 29487603, 2018). "Granule neuron precursors (GNPs) which give rise to medulloblastoma express high levels of the AhR." (PMID 24755659, 2014). "Next, we asked whether AHR also inhibited SMAD3 activation in SHH medulloblastoma." (PMID 31924815, 2020). "Determining to what extent high AHRR expression in human SHH medulloblastoma is associated with elevated TGFβ-SMAD3 signalling will be an important next step to identify patients that may benefit from TGFβ-SMAD3 inhibition and/or AHR agonist therapies." (PMID 31924815, 2020). "We identify a specific role for AHR in regulating the TGFβ-SMAD3 signalling axis in CPCs from these tumours and identify a new role for TGFβ-SMAD3 activity in medulloblastoma CPC differentiation." (PMID 31924815, 2020). "During mouse cerebellar development, for example, both Arnt and AhR are highly expressed in GNPs during their active proliferation phase on postnatal days 5–6, suggesting that Arnt might maintain GNPs and possibly derivative medulloblastoma cells in an undifferentiated state." (PMID 25059231, 2014). "In an immortalized cell line of medulloblastoma (DAOY cells) with a knockdown of AhR, in which the AhR protein level is decreased by 70% as compared to wild-type DAOY cells, cell cycle disturbances, decreased DNA synthesis, and decreased proliferation are observed." (PMID 32325928, 2020).
medulloblastoma (continued). "They suggested that abnormal activation or suppression of the AhR could dysregulate the cycle of granule neuron precursor (GNP) cells and that the AhR could promote the proliferation of medulloblastoma cells." (PMID 29487603, 2018).
fibrosis (12 papers, 2018 to 2024). the formation of excess fibrous connective tissue in an organ or tissue in a reparative or reactive process. "Important canonical pathways linked to the top network were hepatic cholestasis, hepatic fibrosis/hepatic stellate cell activation, hepatic fibrosis signaling pathway, Il-6 signaling, B cell receptor signaling, estrogen-mediated S-phase entry, and aryl hydrocarbon receptor signaling." (PMID 38068980, 2023). "PEMT, AHR, and PC levels are elevated in simple steatosis patients, but PC levels are robustly reduced in steatohepatitis-fibrosis patients." (PMID 29416063, 2018). "Notably, in severe NASH-fibrosis patients, hepatic PC and PE levels are dramatically decreased even though hepatic AHR and PEMT levels are elevated." (PMID 29416063, 2018). "We have demonstrated a role for DC AHR signaling in the exacerbation of virally induced post-BMT pneumonitis and fibrosis." (PMID 33491663, 2021). "Hepatic mRNA levels and protein levels of PEMT and AHR were significantly elevated in both mild simple steatosis and severe NASH-fibrosis patients compared to normal individuals, while SHP mRNA levels were not significantly changed." (PMID 29416063, 2018). "In human orbital fibroblasts, AhR activation by the AhR ligand 6-formylindolo [3,2b]carbazole (FICZ) led to the expression of MMP-1 in an AhR- and ARNT-dependent manner and decreased collagen levels in a fibrosis model." (PMID 37108212, 2023). "AHR was predicted to be involved in Fibrosis of Liver aspects, however, this result was not included as samples were derived from adipose tissue." (PMID 30080895, 2018). "In addition to the canonical AhR signaling pathway, kynurenine also accelerates cardiac fibrosis through the non-canonical AhR signaling pathway." (PMID 35656117, 2022).
ischemia (12 papers, 2016 to 2025). A hypoperfusion of the BLOOD through an organ or tissue caused by a PATHOLOGIC CONSTRICTION or obstruction of its BLOOD VESSELS, or an absence of BLOOD CIRCULATION. "While the AhR pathway has been implicated in the pro-migratory effects of astrocyte activation, our data suggest that resveratrol (Rsv) attenuates ischemia-induced astrogliosis through an AhR-independent mechanism." (PMID 41452851, 2025). "Microglial AhR can induce oxidative stress and inflammatory reactions during ischemia, which causes vasogenic edema progression and subsequent brain injury." (PMID 33804845, 2021). "Although previous studies reported activation of AHR by MG132 to alleviate liver injury in in vivo and in vitro models of intestinal ischemia/reperfusion, the mechanisms underlying the effect of AHR activation on intestinal barrier damage following invasive C. albicans infection remain unknown." (PMID 35923391, 2022). "The AhR-/- control group had a significantly enhanced HIF-1α expression compared to the AhR+/+ control group as well as at the three-h post-ischemia group (*p = 0.0242)." (PMID 41452851, 2025). "In contrast, both the pharmacological blockade with Rsv in AhR+/+ and AhR-/- after ischemia improved locomotor activity 24 h and five days later compared with the ischemic-AhR+/+ group (*p = 0.0149)." (PMID 41452851, 2025). "Analysis using both the CRM28 core, in which chemical substances attached to CRM28 were removed, and AhR KO mice indicated that PAHs contained in CRM28 caused enhanced neuroinflammation and exacerbation of motor dysfunction after ischemia." (PMID 36797786, 2023). "The neuroprotective action of AhR antagonism against ischemia likely involves an inhibition of apoptosis and autophagy." (PMID 34830207, 2021). "DIM (1, 10 μM) partially normalized ischemia-induced changes i.e., it reduced the AhR, CYP1A1, Fas, and BECN1 immunolabeling." (PMID 30778709, 2019). "Recently the effect of IS on HIF in response to ischemia was demonstrated as well as the key role of AhR in IS effect on EPO transcription under hypoxic condition." (PMID 28747155, 2017). "In this regard, it has been reported that the excitotoxic process activated during ischemia leads to myelin injury and that a knockdown or blocking of the aryl hydrocarbon receptor mitigates excitotoxicity, and this could be related to less damage to myelin." (PMID 41452851, 2025). "The AhR regulates inflammatory cytokines in many diseases driven by immune/inflammatory processes, and its absence appears to foster a less hostile inflammatory environment post-ischemia." (PMID 41452851, 2025). "Furthermore, we found that IL-6 expression was higher 3- and 5-day post-ischemia in the hippocampus of AhR+/+ mice compared with AhR-/- mice (*p = 0.0377; **p = 0.0091), supporting the role of AhR in exacerbating the neuroinflammatory response to ischemia." (PMID 41452851, 2025). "This potential interaction is a critical consideration for interpreting AhR activity in our ischemia model, as the transcriptional consequences of AhR activation or inhibition may be influenced by this crosstalk." (PMID 41452851, 2025). "The role of AhR in neuroinflammation is still controversial, but AhR might be proinflammatory, at least in ischemia." (PMID 36797786, 2023). "We hypothesize that activation of ERs and PPARs and inhibition of AhR signaling pathways could be a promising strategy to protect the heart and the brain against ischemia." (PMID 34830207, 2021). "Thus, the purpose of this study was to examine the role of AhR in inflammation and edema after ischemia using a mouse middle cerebral artery occlusion (MCAO) model." (PMID 33804845, 2021). "In addition, the expression levels of IL-1β and cyclooxygenase-2 (COX-2) were also elevated 3 h after MCAO, and administration of CH223191 clearly suppressed the increment, showing that AhR-mediated inflammation occurs during ischemia." (PMID 33804845, 2021).
ischemia (continued). "The results presented here support the hypothesis that the absence or pharmacological blockade of the AhR promotes a neuroprotective effect, and the data allows us to suggest the potential of the pharmacological modulation of the activity of the AhR in ischemia treatment." (PMID 41452851, 2025). "Moreover, the AhR-knockout induces a neuroprotective effect after a neurotoxic injury, and in a transgenic model of Huntington ́s disease, and it has also been related to pathophysiological phenomena such as ischemia, trauma, and neurodegenerative diseases." (PMID 41452851, 2025). "The activities of COX have a critical role in tight junction dysregulation, and the AhR affects target genes such as COX2; thus, the absence of the AhR could explain the 5-day-post-ischemia increase in claudin 5 associated with BBB recovery." (PMID 41452851, 2025). "However, BCCAO-induced ischemia leads to severe microvessel injury in AhR+/+ mice." (PMID 41452851, 2025). "Therefore, inflammation accompanied by ischemia can increase AhR expression." (PMID 33804845, 2021). "Therefore, microglial AhR is considered to be functional during ischemia." (PMID 33804845, 2021). "We showed in this study that microglial AhR expression was upregulated during ischemia and that microglial AhR could be involved in oxidative stress and subsequent inflammatory reactions, suggesting that AhR plays a fundamental role in the pathological process of ischemia." (PMID 33804845, 2021). "Hindlimb ischemia in adenine-induced CKD and IS solute–specific mouse models showed diminished β-catenin and VEGF-A in the capillaries and reduced capillary density, which correlated inversely with blood levels of IS and Kyn and AHR activity in ECs." (PMID 34752422, 2022). "During ischemia injury, fibroblasts participate in cell repair by expressing and secreting collagen, while KYN can inhibit the collagen expression of fibroblasts by activating AhR." (PMID 36292942, 2022).